RN7SL519P (RNA, 7SL, cytoplasmic 519, pseudogene)
Gene: Miscellaneous RNA gene on chromosome 12 (50,841,498 to 50,841,785, reverse strand). Ensembl gene ENSG00000243075.
Homologues: Orthologues: chimpanzee Metazoa_SRP (97% identical), macaque Metazoa_SRP (86% identical). Paralogues in human: RN7SL1 (80% identical), RN7SL2 (79% identical), RN7SL431P (79% identical), RN7SL113P (78% identical), RN7SL187P (78% identical), RN7SL218P (78% identical), RN7SL478P (78% identical), RN7SL556P (78% identical), RN7SL788P (78% identical), RN7SL220P (77% identical), RN7SL320P (77% identical), RN7SL660P (77% identical), and 702 more.